ISG20 (interferon stimulated exonuclease gene 20)
Diseases named in the same sentence as ISG20 in open-access papers (continued):
Sharing a sentence is not in itself a finding about the gene and the disease.
glioma (continued). "ISG20 is expressed in M2 macrophages and can serve as a novel indicator for predicting malignant phenotypes and clinical prognosis in glioma patients." (PMID 37380984, 2023). "To further clarify the functional role of ISG20 in gliomas, we performed an enrichment analysis based on DEGs between the high and low ISG20 expression groups." (PMID 37380984, 2023). "Kaplan–Meier survival analysis showed that glioma patients with elevated ISG20 expression presented with unfavorable OS (P < 0.001, HR = 4.73, 95% CI: 3.67–6.11)." (PMID 37380984, 2023). "Stratifying by WHO grade, ISG20 expression was highest in G4 gliomas, followed by G3 and G2 gliomas (P < 0.001)." (PMID 37380984, 2023). "ISG20 protein expression was higher in high-grade glioma (G4) than in low-grade glioma (G2 and G3), consistent with the results of the transcriptional analyses (P < 0.05)." (PMID 37380984, 2023). "In human gliomas, patients expressing high ISG20 had a poor prognosis, which was inconsistent with our study." (PMID 37964257, 2023). "ISG20 is a 20 kDa protein that was capable of inhibiting multiple viruses and its expression was shown to contribute to poor survival in glioma." (PMID 36816023, 2023). "We also confirmed the expression pattern of ISG20 in glioma patient samples by immunohistochemistry and immunofluorescence staining." (PMID 37380984, 2023). "ISG20 was also found to support tumor progression in hepatocellular carcinoma, glioma, oral cancer, and renal cell carcinoma." (PMID 34078871, 2021). "In human glioma, ISG20 was positively correlated to immune checkpoints (PD-1 and PD-L1) and suppressed the adaptive immune response." (PMID 32003757, 2020). "ISG20 mRNA expression was higher in glioma tissues than in normal tissues." (PMID 37380984, 2023). "To further explore the expression pattern of ISG20 in glioma, we analyzed the expression of ISG20 in patient subgroups with disparate clinical characteristics, including age, gender, IDH mutation, 1p19q co-deletion, MGMT methylation, WHO grade, histology, and primary therapy outcome." (PMID 37380984, 2023). "This might be attributed to the great discrepancy in the two comparing groups (166 cases of G4 glioma presented high expression of ISG20, while only 6 cases of G4 glioma expressed low level of ISG20)." (PMID 37380984, 2023). "Analysis of tumor purity, the level of stromal cells that are present, and the infiltration level of immune cells resolved by ESTIMATE revealed that glioma samples with enhanced ISG20 expression manifested increased immune, stromal, and ESTIMATE scores (all P < 0.001)." (PMID 37380984, 2023). "Furthermore, immunohistochemistry staining confirmed the enhanced expression of ISG20 in glioma tissues with a higher WHO grade, and immunofluorescence assay verified its cellular localization on M2 macrophages." (PMID 37380984, 2023). "Finally, immunohistochemical staining showed upregulation of ISG20 in glioma tissues with a higher WHO grade, and the immunofluorescence assay verified that ISG20 was expressed in M2 macrophages." (PMID 37380984, 2023). "This might be attributed to the small sample size of ISG20 low glioma patients (n = 6) in the G4 subgroup to draw any reliable conclusions." (PMID 37380984, 2023). "Further exploration of the prognostic value of ISG20 revealed that higher expression was associated with a shorter OS in ACC, DLBC, LAML (acute myeloid leukemia), LGG (lower grade glioma), and UVM (uveal melanoma), but with a long OS in CESC, OV (ovarian serous cystadenocarcinoma), and SKCM." (PMID 36177004, 2022). "The expression of ISG20 is reduced in IDH mutant tumors and ISG20 can promote local tumor immunity and may serve as a potential therapeutic target of human glioma." (PMID 31803541, 2019). "Finally, we verified the protein expression pattern of ISG20 in clinical glioma specimens." (PMID 37380984, 2023). "Additionally, GSEA was performed to identify ISG20 related biological functions in gliomas." (PMID 37380984, 2023).
glioma (continued). "In addition, high expression of ISG20 predicted poor overall survival in glioma." (PMID 32003757, 2020). "In particular, glioma tissues (LGG and GBM) uniformly expressed higher levels of ISG20 than normal brain tissues did, and the difference was most significant in GBM, the most aggressive subtype of glioma." (PMID 37380984, 2023). "Several reports also suggest a link between ISG20 and the tumorigenic process of multiple neoplasms, including glioma, oral tumor, clear cell renal cell carcinoma, hepatocellular carcinoma, breast cancer, and acute myeloid leukemia, although the exact ISG20 pathomechanism remains unclear." (PMID 37380984, 2023). "Moreover, the time-dependent ROC analysis revealed that the ISG20 expression had a relatively good performance in predicting 1-year (AUC = 0.84, 95% CI: 0.80–0.88), 2-year (AUC = 0.88, 95% CI: 0.84–0.91), and 3-year OS (AUC = 0.85, 95% CI: 0.80–0.89) in glioma patients." (PMID 37380984, 2023). "Immunofluorescence assay was performed to further explore the cellular localization of ISG20 and CD163 in glioma samples." (PMID 37380984, 2023). "In terms of 1p19q codeletion status, upregulation of ISG20 was noted in glioma tissues with 1p19q non-codeletion (P < 0.001)." (PMID 37380984, 2023). "Taken together, these results suggest that ISG20 expression might predict the immunosuppressive status of the TME and immune cell infiltration in gliomas, especially macrophage and T cell immune responses." (PMID 37380984, 2023).
hepatocellular carcinoma (12 papers, 2017 to 2024). A malignant tumor that arises from hepatocytes. "Lastly, ISG20, which has been studied in hepatocellular carcinoma and lung cancer, may play a role in modulating the type I interferon response and activating immune cells crucial for antitumor immunity in NBL." (PMID 39559348, 2024). "We employed machine learning algorithms to screen six genes, BATF, CXCR3, GIMAP5, GPR8, IGHM, and ISG20, that have been extensively investigated in other cancers, including lymphoma, melanoma, leukemia, breast cancer, multiple myeloma, hepatocellular carcinoma, and lung cancer." (PMID 39559348, 2024). "Interestingly, the other upregulated genes are associated with features of cell proliferation (TNFRSF12A in human hepatocellular carcinoma), tumor progression (ISG20 in clear cell renal cell carcinoma), and cell survival (LGALS3 in breast cancer)." (PMID 37685859, 2023). "To demonstrate the utility of this system, we show that two interferon-stimulated genes (ISGs), ISG20 and tetherin, restrict HBV spread in NTCP-expressing hepatoma cells." (PMID 29192196, 2017). "We found no significant changes in ISG20 expression, although ISG20 is a protein whose forced expression leads to significant promotion of metastasis and angiogenesis in hepatocellular carcinoma." (PMID 33473258, 2020). "ISG20 mRNA was quantified by qRT-PCR in 30 pairs of hepatocellular carcinoma (HCC) tumour and adjacent non-tumour liver tissues." (PMID 29963243, 2018). "Such difference might be due to the reported weak response of hepatoma cells to IFN treatment, and/or the potential unknown negative regulator(s) of ISG20 co-induced by IFN." (PMID 28399146, 2017).
breast carcinoma (10 papers, 2018 to 2025). "STAT5A has been found to be negatively correlated with interferon-stimulated exonuclease gene 20 (ISG20) expression in breast cancer, where ISG20 is upregulated in metastases and is associated with aggressive and invasive tumor behavior." (PMID 40507264, 2025). "ISG20 staining showed high expression in the cytoplasm and membranes in the breast tissues and breast cancer tissues." (PMID 36177004, 2022). "We used PuMA to investigate if breast cancer cells with elevated ISG20 expression will show efficient lung colonization." (PMID 34078871, 2021). "Our findings revealed that increased ISG20 promotes invasive phenotype of human breast cancer cells." (PMID 34078871, 2021). "Here we show that ISG20 expression is increased in metastatic tissues compared to their matched primary breast cancer tissues." (PMID 34078871, 2021). "Studies have documented an induction of ISG20 in cervical and breast cancer cell lines and up-regulation of ISG20 mRNA in cervical tumours compared to normal cervix tissues." (PMID 29963243, 2018). "In addition, our analysis identified an IFN-responsive neutrophil population with high expression of IFN-responsive genes (Ifit3, Ifit1, Ifit3b, Ifi47, Ifitm3, Rsad2, Isg15, and Isg20), which is more present in metastatic lung of breast cancer." (PMID 37483625, 2023). "Taken together our findings demonstrate metastasis promoting role of ISG20 in breast cancer." (PMID 34078871, 2021). "Thus, to investigate its role in breast cancer, we stained for ISG20 in 96 human breast samples on an array consisting of normal tissues, primary breast tumor or lymph node (LN) metastasis." (PMID 34078871, 2021). "Additionally, we examined ISG20 expressions across publicly available RNA sequencing data of 1247 breast cancer patients and found that ISG20 levels are significantly higher in breast tumor tissues compared to normal mammary tissues (p ≤ 0.0001)." (PMID 34078871, 2021). "All these observations provide a strong indication that NMI might be negatively regulating ISG20 in breast cancer cells." (PMID 34078871, 2021). "However, the details of regulation and functional role of ISG20 in cancers, specifically in breast cancer still remain unknown." (PMID 34078871, 2021). "We found the expression of ISG20 to be inversely correlated with NMI expression in NMI knockout mammary tumor mouse model and as well in human breast cancer cell lines." (PMID 34078871, 2021). "A similar prediction could be made using five genes most differentially expressed in the breast cancer stroma, PSPHL, CXCL10, CXCL11, ISG20, and GMDS." (PMID 32714862, 2020). "Interestingly, CXCL10, CXCL11, and ISG20 are IFN-γ-regulated genes, which is consistent with the presence of interferon signature found in breast cancer from AA patients." (PMID 32714862, 2020). "Role of ISG20 has never been described in metastatic process of mammary tumors." (PMID 34078871, 2021). "We observed that ISG20 expression is significantly elevated in metastatic lymph nodes tissues compared to its matched primary tumors; this suggests that ISG20 might have a role in the complex process of breast cancer metastasis." (PMID 34078871, 2021). "However, the results showed that UMP did not affect ISG20 mRNA expression in A549 lung cancer cells, HeLa cervical cancer cells, 22RV1 and PC3 prostate cancer cells, and MDA-MB-231 and BT549 breast cancer cells ​." (PMID 36177004, 2022).
clear cell renal cell carcinoma (8 papers, 2020 to 2025). "Whereas, high ISG20 expression was found to significantly associated with poor prognosis in liver cancer and clear cell renal cell carcinoma, which was proved to enhance angiogenesis, tumor cell proliferation and metastasis." (PMID 36639648, 2023). "In renal clear cell carcinoma, ISG20 positively regulates the expression of CCND1, which promotes cell proliferation and upregulates the expression of MMP9, which is involved in the breakdown of the extracellular matrix and promotes metastasis." (PMID 39428941, 2025). "A study in clear cell renal cell carcinoma identified ISG20 as a potential biomarker and therapeutic target for clear cell renal cell carcinoma which promoted cell proliferation and metastasis." (PMID 35812403, 2022). "Given the reported roles of Isg20 in lupus nephritis and clear-cell renal-cell carcinoma, our results highlight the pivotal and multifaceted roles of Isg20 in renal disorders; furthermore, Isg20 likely facilitates ribosome biogenesis to promote renal fibrosis progression." (PMID 40622935, 2025).
renal fibrosis (8 papers, 2021 to 2025). A final common manifestation of a wide variety of chronic kidney diseases characterized by glomerulosclerosis and tubulointerstitial fibrosis. "It was further indicated that inhibition of NFAT5 reversed the pathological conditions such as renal fibrosis caused by oe‐lnc‐ISG20." (PMID 33939247, 2021). "In vitro experiments were applied to examine the function of ISG20 knockdown on the progression of renal fibrosis." (PMID 35497880, 2022). "The results of Western blot and PCR revealed that knockdown of ISG20 distinctly suppressed the expression of the expressions of fibrotic proteins (α-SMA and fibronectin), indicating ISG20 promoted the progression of renal fibrosis." (PMID 35497880, 2022). "In view of this, the current study performed a series of experiments, and our findings demonstrated that lnc‐ISG20 was highly expressed in DN patients, and exhibited a close relationship with renal fibrosis." (PMID 33939247, 2021). "Our collective findings indicate that lnc‐ISG20 promotes the renal fibrosis process in DN by activating AKT through the miR‐486‐5p/NFAT5 axis." (PMID 33939247, 2021). "Based on all above findings, our study indicates towards the existence of a regulatory axis in the pathophysiology of DN, wherein lnc‐ISG20 promotes renal fibrosis via the miR‐486‐5p/NFAT5/p‐AKT pathway." (PMID 33939247, 2021). "Accordingly, we found that lnc‐ISG20 promoted renal fibrosis in DN through impairing miR‐486‐5p‐dependent inhibition of NFAT5 and activating AKT." (PMID 33939247, 2021). "The effect of lnc‐ISG20 and miR‐486/NFAT5/p‐AKT axis on DN‐associated renal fibrosis was also verified by means of rescue experiments." (PMID 33939247, 2021). "We aimed to elucidate the function and regulatory mechanism of lncRNA lnc‐ISG20 on DN‐induced renal fibrosis." (PMID 33939247, 2021). "RT-PCR was used to examine the expression of ISG20 in renal fibrosis and healthy samples." (PMID 35497880, 2022). "ISG20 siRNA significantly suppressed the progression of renal fibrosis in vitro." (PMID 35497880, 2022). "In this study, our data revealed that knockdown of lnc‐ISG20 could inhibit the renal fibrosis of DN, and lnc‐ISG20 could inhibit the expression of miR‐486‐5p which was further found to be able to inhibit the AKT phosphorylation via NFAT5." (PMID 33939247, 2021). "Lnc‐ISG20 silencing alleviated HG‐induced fibrosis in MCs and delayed renal fibrosis in DN mice." (PMID 33939247, 2021). "Moreover, the high‐expression pattern of lnc‐ISG20 in DN and its correlation with renal fibrosis indicate that lnc‐ISG20 can serve as a promising biomarker for the renal fibrosis in DN." (PMID 33939247, 2021). "Here, these results provide evidence for that lnc‐ISG20 could promote the renal fibrosis in DN via miR‐486‐5p/NFAT5/AKT." (PMID 33939247, 2021). "ISG20 could be a novel therapeutic target of renal fibrosis." (PMID 36330810, 2022). "Expanding on this role, we identified that lnc‐ISG20 served as an upstream regulator for miR‐486‐5p in DN, in which lnc‐ISG20 could down‐regulate the expression of miR‐486‐5p and thus relieve its inhibitory effect, resulting in the promotion of renal fibrosis." (PMID 33939247, 2021). "Additionally, the current study demonstrated that lnc‐ISG20 could promote cell fibrosis in MCs, while silencing of lnc‐ISG20 in DN mice brought about inhibitory effects on renal fibrosis." (PMID 33939247, 2021). "Also, whether lnc‐ISG20 acts in cell types other than MCs such as renal tubular epithelial cells in renal fibrosis is necessary to be investigated in the future." (PMID 33939247, 2021). "One such lncRNA, lnc‐ISG20 was documented to exhibit up‐regulated expression levels in the glomerular of DN patients, while miR‐486‐5p was correlated with blood glucose or albuminuria, all of which enable non‐coding RNAs to serve as promising biomarkers for DN or renal fibrosis." (PMID 33939247, 2021).
renal fibrosis (continued). "In summary, we identified five key genes (SFN, ARHGAP9, VSIG4, ISG20, CD3G) that can distinguish patients with renal fibrosis from controls, making them potential biomarkers for disease diagnosis and treatment monitoring." (PMID 41218386, 2025). "The expression of ISG20 and SERPINA3 was distinctly increased in renal fibrosis samples compared with normal samples." (PMID 35497880, 2022). "We found that both ISG20 and SERPINA exhibited a higher level in renal fibrosis than normal specimens." (PMID 35497880, 2022). "Recently, the lncRNA lnc‐ISG20 was found to be up‐regulated in the glomerular in DN patients, but the actual mechanism remains unclear, based on which we set out to elucidate the molecular mechanism of lnc‐ISG20 in regulating the progression of renal fibrosis in DN." (PMID 33939247, 2021). "The expression of ISG20 was significantly elevated in renal fibrosis compared to normal samples, and in vitro knockdown of ISG20 significantly inhibited fibrotic protein expression in HK-2." (PMID 36814902, 2023). "In addition, Duan YR and colleagues highlighted that lnc-ISG20 facilitated NFAT5 through inhibiting miR-486-5p and induced renal fibrosis in diabetic nephropathy." (PMID 35012431, 2022). "Finally, we observed that the expression of ISG20 and SERPINA3 was distinctly increased in renal fibrosis samples compared with normal samples." (PMID 35497880, 2022). "Hence, these findings indicated that lnc‐ISG20 stimulated AKT phosphorylation and promoted renal fibrosis in DN mice by inducing NFAT5." (PMID 33939247, 2021).
cervical carcinoma (7 papers, 2015 to 2025). A carcinoma arising from either the exocervical squamous epithelium or the endocervical glandular epithelium. "It has been reported that ISG20 is up-regulated in cervical cancer." (PMID 32003757, 2020). "The ability of SM to inversely down-regulate EFNA1 and TFRC and up-regulate HIST1H2BK and ISG20 could illustrate a probable importance of these genes in SM-induced inhibition of growth of cervical carcinoma cells." (PMID 31523389, 2019). "In addition, ISG20 was also reported to be differentially expressed in cervical cancer tissues." (PMID 34498424, 2021). "As ISG20 participates in the antiviral response, we hypothesised that ISG20 might participate in the anti‐HPV immune response by activating T cells or DCs and thus influence the overall survival of cervical cancer patients." (PMID 34498424, 2021). "Furthermore, we also investigated the therapeutic value of the six‐gene signature and found that it could help predict the response to immune checkpoint inhibitors (ICIs) and that three genes (GLTP, ISG20 and UPP1) in the six‐gene signature might serve as potential drug targets for cervical cancer." (PMID 34498424, 2021).
liver cancer (7 papers, 2018 to 2025). An epithelial or non-epithelial malignant neoplasm that arises from the liver. "Our results showed that m62A increased ISG20 expression at both the protein and mRNA level in a dose-dependent manner in the HepG2 liver cancer cell line ​." (PMID 36177004, 2022). "ISG20 has interferon-related antiviral effects, while a study found that over-expression of ISG20 promotes metastasis and angiogenesis of liver cancer cells." (PMID 32547879, 2020). "A recent study has shown that forced expression of ISG20 promotes metastases and angiogenesis via the IL-8/p-JAK2/p-STAT3 signalling pathway, both in liver cancer cell lines and in animal models, suggesting a pro-tumour role of ISG20." (PMID 29963243, 2018). "Additionally, it was also reported that both in vivo and in vitro, the up-regulation of ISG20 significantly promoted angiogenesis in liver cancer cells." (PMID 40564394, 2025). "ISG20 has been reported to be a major effector of innate immune responses against various pathogens, including viruses, bacteria, and parasites, and ISG20 is also involved in angiogenesis in liver cancer." (PMID 38343536, 2024). "ISG20 is an interferon-induced exoribonuclease and usually acts on single-stranded RNA and exerts little effect on single-stranded DNA and it may be induced by thyroid hormone and promotes angiogenesis in liver cancer." (PMID 33634092, 2020).